IL4 (interleukin 4)
Diseases named in the same sentence as IL4 in open-access papers (continued):
Sharing a sentence is not in itself a finding about the gene and the disease.
asthma (continued). "We found that patients experiencing an asthma attack, when compared with patients in asthma remission, showed significantly elevated serum mTOR pathway activation, increased Th17 cells and IL-4, and decreased Treg cells and IFN-γ." (PMID 28674387, 2017). "In humans, blocking receptors for IL-4 and IL-13 improves lung function and reduces the frequency of exacerbations in individuals with moderate-to-severe asthma with high levels of eosinophils." (PMID 28670318, 2017). "Mice that lack key Th2 cytokines such IL-4 or IL-13 had substantial reductions in asthma features in the OVA model." (PMID 28670318, 2017). "This gene set includes numerous cytokines that mediate Th2 cell signaling associated with asthma (IL3, IL4, IL5, IL9, IL10 and IL13), as well as components of the IgE receptor (FCERA, FCERG, MS4A2) and eosinophil granule proteins (ECP, EDN, EPX, and MBP)." (PMID 28854632, 2017). "Type 2 cytokines, particularly IL-4 and IL-13, are important in the pathogenesis of human asthma and murine allergic airway disease, which is a useful, albeit imperfect, model of human asthma." (PMID 29182669, 2017). "Studies on T helper 2 (Th2) cytokines in asthma have focused on IL-4 and IL-5 and this is due to the crucial role of these two cytokines in Th2 generation responses in a variety of animal models." (PMID 28386156, 2017). "Compared with the asthma model group, the serum levels of IL-4, IL-5 and IgE in each group of drug administration was remarkably decreased (P < 0.01)." (PMID 28764781, 2017). "S1P is suggested to contribute to airway hyperreactivity and release of IL-4 and IL-13, thereby involving in asthma pathogenesis." (PMID 28659663, 2017). "The mechanisms of asthma and rhinitis were identical for the IL4 signaling pathway and the 4-1BB-dependent immune response pathways." (PMID 28598986, 2017). "In asthma, IL-6 is upregulated in pulmonary epithelial cells by various stimuli and is involved in facilitating IL-4 differentiation, downregulating Th2 cell differentiation, and promoting Th17 cell differentiation." (PMID 29151835, 2017). "The stratification of patients in clinical trials based on specific endotypes has lent support for continued efforts to modify IL-4 and IL-13 pathways in type-2-high asthma, yet additional variation in treatment response is still apparent." (PMID 28721208, 2017). "We found an association between IL-17 and IL-5 with difficult-to-control asthma, in comparison to previous studies which report IL-4+IL-17+ or IL-13IL-17+ T-cell populations." (PMID 28686637, 2017). "Th2/Th17 predominant (IL-4/IL-17 dual-positive Th cells) cells have been reported in patients with severe asthma." (PMID 28740493, 2017). "Levels of IL-3, IL-4, and IL-5 correlated well with the eosinophil counts in tissue in asthma with CRS." (PMID 28199345, 2017). "The levels of IL-4, IL-6, and IL-12 in children with moderate and severe asthma were close to the levels of those in normal control group after treatment (all P > 0.05)." (PMID 28328807, 2017). "The asthma and obesity groups showed an increase in cytokine of IL-17A, IL-4, IL-6, TNF, IL-1β and IL-18 in the BALF compared with normal controls." (PMID 29160418, 2017). "The ration of IFN-γ/IL-4 in the group treated with high concentration of the extract was significantly increased compared with the untreated asthma group (p < 0.01)." (PMID 28824424, 2017). "Level serum IgE was significantly increased in TDI-induced murine asthma model, as well as IL-4 in supernatant of cultured lymphocytes, the number of inflammatory cells and the protein level of HMGB1 in BAL fluid and lung tissue." (PMID 28630596, 2017). "This study demonstrated that IL-4, IL-6, and IL-12 levels in PB were associated with lung function, cellular immune function, and QOL in children with moderate-to-severe asthma." (PMID 28328807, 2017).
asthma (continued). "Inhalation of an ASO targeting Mex-3B suppressed airway eosinophilia, lung inflammation, mucus hypersecretion, and BAL fluid levels of Th2 cytokine IL-4, IL-5 and IL-13 in an experimental model of asthma." (PMID 28106744, 2017). "Th2 cells predominantly secrete cytokines interleukin (IL)-4, IL-5, IL-9 and IL-13, which play a central role in the pathophysiology of asthma." (PMID 28931396, 2017). "Th2 lymphocytes play a critical role in the initiation and progression of allergic diseases, including atopic dermatitis and asthma, by releasing IL-4, IL-5, and IL-13." (PMID 29062168, 2017). "The levels of IL-4, RBC-C3bR, FEV1/FVC, and PEF were independent risk factors for the prognosis of treatment for children with moderate-to-severe asthma." (PMID 28328807, 2017). "Increased IL-4 expression is found during chronic inflammatory conditions (e.g. asthma, allergic inflammation and AD) that are also characterized by increased influx of monocytes/macrophages to the lesions." (PMID 29203829, 2017). "Th2 cytokines (IL-4, IL-5, and IL-13) are known to be critically involved in the pathogenesis of asthma." (PMID 28746467, 2017). "The results revealed that the levels of IL-4, RBC-C3b, FEVE/FVC, and PEF were independent risk factors for prognosis of children with moderate-to-severe asthma (all P < 0.05)." (PMID 28328807, 2017). "O. humifusa effectively suppressed OVA-induced asthma by modulating Th1-/Th2-/Th17-related cytokines; in particular, Th2-related cytokines such as IL-4 and IL-13 were downregulated." (PMID 29151835, 2017). "Asthma is characterized by type 2 immune responses and production of cytokines such as IL-4, IL-5 and IL-13 that drive the allergic disease." (PMID 28830530, 2017). "Monoclonal antibodies directed against IgE, IL-4 and 13 and IL-5 have been extensively studied in asthma, and one anti-IgE and two anti-IL-5 monoclonal antibodies have been approved by the US FDA for the treatment of severe asthma." (PMID 28855973, 2017). "Once activated, ILC2s release IL-4 and IL-13 that are main keys to the inflammatory features on asthma." (PMID 28670318, 2017). "The role that interleukin-4 plays in the pathogenesis of asthma has been indicated from actively sensitized IL-4 knockout mice." (PMID 28386156, 2017). "OVA-IgE, IL-4, IL-5, IL-13 and INF-gamma in BALF was also increased in TLR2-deficient mice treated with B7-H3, which suggest in OVA-induced asthma model B7-H3 augment the inflammatory response independent of TLR2 pathway." (PMID 28094276, 2017). "CD8α+ DCs enhance cross-priming of CD8+ T cells redirecting the immune response in asthma away from Th2 response, as shown here with decrements of IL-4 and IL-13 levels, decreased number of eosinophils." (PMID 28670318, 2017). "There were 15 pathways involved in the multimorbidity of asthma, eczema and rhinitis, including IL4 signaling and GATA3-related pathways." (PMID 28598986, 2017). "It is initially discovered that IL-4 and IL-6 levels were increased, whereas IL-12 level was decreased in PB of the asthma patients." (PMID 28328807, 2017). "We and others previously found that pendrin/SLC26A4, an anion transporter located at the apical side of airway epithelial cells, is a downstream molecule of the IL-4/IL-13 signals that plays an important role in the pathogenesis of asthma." (PMID 29359006, 2017). "Dupilumab, a humanized monoclonal antibody to IL-4Rα that inhibits both IL-4 and IL-13 signaling, is being assessed in patients with uncontrolled asthma." (PMID 29034234, 2017). "Therefore, changes in IFN-γ/IL-4 cytokines ratio (Th1/Th2 balance) toward IL-4 (Th2) may cause allergic and atopic diseases such as atopic dermatitis, anaphylactic shock, allergic rhinitis, and asthma." (PMID 28824424, 2017). "IL-17 and IL-4 were significantly higher in the asthma attack group than in the other three groups, whereas TGF-β, IL-10, and IFN-γ were significantly lower." (PMID 28674387, 2017).
asthma (continued). "Th2 cells expressing IL-4, -5, and -13 constitute a defense against extracellular pathogens and are involved in atrophy and asthma." (PMID 28235034, 2017). "To determine the anti-asthmatic effects of pitavastatin on cytokine levels in mice with asthma, we measured IL-4, IL-17, and IFN-γ production in BALF by ELISA, according to the manufacturer’s instructions." (PMID 28729731, 2017). "Overproduction of Th2 cytokines, such as IL-4 and IL-5 which are released by Th2 cells, is shown to contribute to the pathophysiology of asthma." (PMID 28623898, 2017). "Our data indicated that risk alleles located in ADAM33 rs2280090 and rs3918396, IL4 rs2243250 and CD14 rs2569190 are associated in allergy, asthma, and other related phenotypic traits such as wheezing and atopy." (PMID 27624002, 2016). "The asthma group had significantly higher IL-4 levels compared with the normal control group (p < 0.001) and givinostat group (p = 0.012)." (PMID 27565183, 2016). "IL-4/IL-4R antagonists have also been evaluated in clinical trials, but improvements in asthma symptoms were limited or inconsistent across studies." (PMID 26922672, 2016). "TLR7 stimulation suppresses eosinophilic airway inflammation in a variety of animal models of asthma through reducing Th2 cytokines such as IL-4 and IL-5 as well as eotaxin in the lung and IgE." (PMID 27274620, 2016). "Targeted therapies at IgE, interleukin-4 (IL-4), IL-4 receptor, IL-5, IL-13, tumor necrosis factor-α, and CRTh2 are new treatment paradigms for asthma." (PMID 27274620, 2016). "Further, considering the inflammatory mediators involved in asthma, kuwanon G significantly decreased the levels of IL-4, IL-5, and IL-13 in the sera and in bronchoalveolar lavage of asthma mice." (PMID 27445433, 2016). "The plasma levels of IL-4 were increased by 21.1% in the patients with asthma but decreased by 55.3% and 26.3% in AR and AR + AS." (PMID 27057098, 2016). "We have revealed for the first time that PTP-RR is also expressed in PBMCs and the U937 human monocytic cell line, and shows reduced expression in severe asthma and IL-2/IL-4-induced corticosteroid insensitivity, respectively." (PMID 27013170, 2016). "Asthma symptoms are related to the presence of activated Th2 cytokine-producing cells (IL4, IL5, IL9 and IL13) in the airway wall." (PMID 26986948, 2016). "As it is known, inflammatory mediators, such as Th2 cells, producing IL-4, IL-5 and IL-13 contribute to not only inflammation but also airway remodeling in asthma." (PMID 27590515, 2016). "When GFBB was used in patients suffering from HDM-induced allergy and asthma, the peak expiratory flow was increased and the production of systemic Th2 cytokines (IL-4, IL-5 and IL-13) was reduced." (PMID 26003185, 2016). "IL-4 and IL-13 can be produced by a variety of cell types of the innate immune system, which plays a crucial role during asthma." (PMID 27716424, 2016). "Asthma is typically thought to be marked by a shift towards Th2-dependent processes, both an early-phase response involving IL-4 and IL-13 and a late-phase response involving IL-5." (PMID 27965775, 2016). "When patients with mild asthma were nebulized with IL-4, an elevation of eosinophil number in the sputum was observed." (PMID 26003185, 2016). "A dominant Th2 response induces several characteristic features of asthma, including eosinophil recruitment, overproduction of Th2-type cytokines (such as IL-4, IL-5, and IL-13), and elevation in the level of IgE." (PMID 27741312, 2016). "Allergen provocation outside of pollen season in patients with asthma resulted in a decrease in IL-4+ CD4+ cells." (PMID 27799958, 2016). "Further, we found that, compared to WT AMs, the genes in the M2 marker were less upregulated in AQP3−/− AMs in an in vivo asthma model, but, conversely, they were more upregulated by in vitro stimulation with IL-4/13." (PMID 27165276, 2016).
asthma (continued). "In the current study, we aimed to examine miR-221 expression in an asthma model and elucidate the mechanisms regulating interleukin (IL)-4 secretion in mast cells." (PMID 26901347, 2016). "In conclusion, miR-221, which was overexpressed in a murine asthma model, stimulated IL-4 secretion in mast cells through a pathway involving PTEN, p38, and NF-κB." (PMID 26901347, 2016). "We demonstrated that knocking-down PTP-RR reduces GR nuclear translocation with concomitant induction of corticosteroid insensitivity, and that PTP-RR expression was reduced in severe asthma and in the IL-2/IL-4-induced corticosteroid insensitive model." (PMID 27013170, 2016). "Goblet cell hyperplasia, a feature of asthma and other respiratory diseases, is driven by the Th-2 cytokines IL-4 and IL-13." (PMID 27786259, 2016). "To investigate the anti-asthmatic effects of picroside II, we determined the levels of inflammatory cytokines, such as Th1 cytokine (IFNγ), Th2 cytokines (IL-4, IL-5, and IL-13), and asthma related cytokine (IL-33) in the BALF using ELISA kit." (PMID 27870920, 2016). "The OVA-induced airway hypersensitivity model of asthma used here results in eosinophilic inflammation in the lung, pulmonary production of Th2 cytokines (IL-4, IL-5 and IL-13) and serum IgE production." (PMID 27390655, 2016). "In asthma, IL-4 released from Th-2 cells contributes to stimulate proliferation and differentiation of B cells that release IgE to mast cells." (PMID 27590515, 2016). "ELISA analysis showed that picroside II down-regulated the levels of Th2-related cytokines (including IL-4, IL-5, and IL-13) and asthma-related mediators, but it up-regulated Th1-related cytokine, IFNγ in BALF." (PMID 27870920, 2016). "In a multivariate analysis, atopy was broadly related to increased Th2‐like responses to all antigens and PHA, while asthma was only weakly related to mitogen‐induced IL‐4 and IL‐5 responses." (PMID 27042305, 2016). "In contrast to asthma, there is a preferential increase in CD8+ and CD4+ cells associated with the production of interferon gamma, although Th2 cytokines such as IL-4 are also increased in COPD patients." (PMID 26334389, 2016). "IL-4 contributes to airway obstruction in asthma via the induction of mucus hypersecretion in mice and human cell lines, and increases the release of several pro-inflammatory cytokines such as IL-6, GM-CSF and eotaxin from human lung fibroblasts." (PMID 26758251, 2016). "IL-4 and IL-13 are thought to play a crucial role in Th2-characterized inflammatory diseases such as asthma and atopic dermatitis." (PMID 27491073, 2016). "RAO shares many features with human asthma, including an increased number of cells expressing mRNA for interleukin (IL)-4 and IL-5 and a decreased expression of IFN-γ in bronchoalveolar lavage fluid (BALF) of affected horses." (PMID 27651133, 2016). "Lungs of humans with asthma have a characteristic expression pattern of inflammatory cytokines, notable amongst those IL-4, IL-6, IL-13, IL-17A and TNF-α50, 51, 52, indicative of Th2 cells and Th17 cells." (PMID 27087690, 2016). "All these were associated to a Th2-type cytokine profile (with the production of IL-5, IL-13 and IL-4), which is important for the development and maintenance of the Th2 response characteristic of asthma." (PMID 25890178, 2015). "IL-10 and IL-4 production was shown to be induced by peripheral blood leukocytes from patients with asthma after exposure to the mite allergen D. farinae." (PMID 25918735, 2015). "We demonstrated association of ADAM33, IL4 and ORMDL3/GSDMB gene polymorphisms with childhood asthma." (PMID 25768087, 2015). "In conclusion, AT-RvD1 demonstrated significant effects on the IL-4-induced activation of bronchial epithelial cells and consequently the potential to modulate neutrophilic and eosinophilic airway inflammation in asthma." (PMID 26075216, 2015).
asthma (continued). "This would enable higher responses to low levels of IL-17A, IL-4 and IL-13 and thus contribute to more marked inflammatory effects such as those seen in severe asthma." (PMID 25849622, 2015). "Further, decline in the levels of IL-4, IL-5 and IL-13 cytokines and IgE was noted in the animals suffering from asthma." (PMID 26481184, 2015). "Th2 cytokines, especially IL-4 and IL-13, are crucial mediators of asthma, and both are proved to play an important role in up-regulating the eosinophil chemo-attractants of eotaxin." (PMID 26035827, 2015). "In our previous studies using murine models of asthma, the recovery of IL-4, IL-5 and IL-13 in bronchoalveolar lavage (BAL) fluid from female mice was significantly higher than that of male mice." (PMID 26488300, 2015). "Asthma historically was characterized as being a CD4+ TH2-mediated disease with increased production of IL-4, IL-13, and IL-5." (PMID 25772594, 2015). "Signal transducer and activator of transcription 6 (STAT6) and nuclear factor kappa B (NF-κB) have been demonstrated to regulate many pathologic features of asthma, and both are activated by IL-4." (PMID 26075216, 2015). "Possible molecular targets, at least in asthma, are IL-4 and IL-13, both involved in atopy related inflammatory processes, and partly sharing the same receptor." (PMID 26101468, 2015). "In a study of CD4+T lymphocytes of patients with asthma, stimulated with allergens, there was a significant correlation between the degree of methylation and IL-4 concentration." (PMID 25859290, 2015). "Inflammatory cytokines such as IL-4, IL-5 and IL-13 are induced in the lung during asthma exacerbations." (PMID 26048391, 2015). "Various studies have shown that Th type 1 (Th1)-related cytokines (interleukin [IL]-12 and IFN-γ), Th type 2 (Th2)-related cytokines (IL-4, IL-5, and IL-13), and proinflammatory cytokines (IL-1β, IL-6, and TNF-α) are associated with asthma." (PMID 25658604, 2015). "With the exception of IL-12, the mRNA levels of asthma-related cytokines were suppressed, and the mRNA expression of IL-4 and IL-5 was almost completely inhibited." (PMID 25658604, 2015). "In the present work, AT-RvD1 significantly reduced CCL2 and CXCL-8 production in bronchial epithelial cells when compared to cells stimulated with IL-4, demonstrating the potential to reduce both neutrophilic and eosinophilic inflammation in asthma." (PMID 26075216, 2015). "It should be noted that we stained only for IL-13, and therefore we cannot exclude an increase in TH2 cells secreting IL-4 or IL-5 in the more severe asthma clusters." (PMID 25746968, 2015). "A wealth of inflammatory mediators, particularly the Th2-associated cytokines IL-4, IL-5, and IL-13, and the pro-inflammatory mediator TNF-α, contributed substantially to airway inflammation in asthma." (PMID 26343632, 2015). "Based on this concept, pitrakinra, an IL-4Ra double mutein involved in both IL-4 and IL-13 signalling, was developed and tested in asthma clinical trials with favourable results." (PMID 26101468, 2015). "In experimental asthma, transfer of lung basophils worsens ongoing Th2 responses by increasing airway inflammation and local IL-4 and IL-13 expression." (PMID 26284078, 2015). "Cytokines produced by the Th2-type CD4 + T cells (interleukin (IL-4, IL-5, IL-13) in asthma have a central role in orchestrating the inflammatory response." (PMID 25890178, 2015). "These alterations are accompanied by changes in biological markers such as cytokines (IL-4 or IL-5) and allergen-specific IgE, which are crucial mediators in the development of asthma." (PMID 26588845, 2015). "Six studies reported the efficacy of acupoint application for childhood asthma on immune outcomes including immunoglobulin A (IgA), immunoglobulin E (IgE), immunoglobulin G (IgG), immunoglobulin M (IgM), interleukin-4 (IL-4), and interferon-γ (IFN-γ)." (PMID 26000027, 2015).